GLI1 (GLI family zinc finger 1)
Diseases named in the same sentence as GLI1 in open-access papers (continued):
Sharing a sentence is not in itself a finding about the gene and the disease.
medulloblastoma (continued). "By contrast, in a model using serum-starved human medulloblastoma cells treated with SHH, vismodegib resulted two-fold less potent than sonidegib in restraining GLI1 mRNA production." (PMID 34831015, 2021). "A positive feedback loop between GLI1 and the tyrosine kinase HCK has been shown to amplify sonic‐hedgehog signaling in medulloblastoma." (PMID 34569154, 2021). "DYRK1B was demonstrated to work as a positive regulator in humane medulloblastoma cells (DAOY), as siRNA-mediated KD of DYRK1B eliminated SAG-induced GLI1 induction." (PMID 33081032, 2020). "In contrast, IL1RL1, TGFB2, GLI1, and EDNRB was over-expressed in classical, and desmoplastic medulloblastoma, and glioblastoma." (PMID 31973134, 2020). "Specifically, IBET-151 attenuates HH signaling in cells with constitutive GLI1 activity in a SMO-independent fashion in BCC, medulloblastoma, and atypical teratoid/rhabdoid tumor." (PMID 32913560, 2020). "Subversion of this mechanism due to HDAC overexpression or loss of REN, has been shown to induce persistent deacetylation of Gli1, leading to CGCP transformation and subsequent medulloblastoma growth." (PMID 31244888, 2019). "We identified the HH effector GLI1 as a target for dual PI3Kα and mTOR inhibition in SHH-type medulloblastoma and confirmed these results in HH-driven Ewing sarcoma cells." (PMID 31492956, 2019). "This negative regulation of HH signaling by MEK/ERK is similar to medulloblastoma, in which FGF-mediated ERK activation inhibits HH pathway target gene expression including GLI1." (PMID 31867038, 2019). "A search for GLI1-binding proteins in medulloblastoma showed that GLI1 and PIN1 form a physical complex in MED-311FH medulloblastoma cells and that this interaction leads to increased GLI1 protein abundance in vitro." (PMID 30314361, 2018). "Medulloblastoma with CD15+ cells expressed higher levels of Shh target genes, such as GLI1 and CYCLIN-D1, than that with CD15− cells." (PMID 30423843, 2018). "When the Hh pathway was blocked by KAAD–cyclopamine, the expression of GLI1 and NANOG was reduced, and the self-renewal of medulloblastoma neurospheres was also significantly inhibited." (PMID 30423843, 2018). "First, in medulloblastoma cells, AMPK phosphorylates the SHH pathway transcription factor GLI1, promoting its proteasomal degradation, thus inhibiting SHH signaling and SHH-driven medulloblastoma." (PMID 30360486, 2018). "Amplification of GLI1 and GLI2 loci has been detected in medulloblastoma, the most common malignant brain tumor in children." (PMID 30158435, 2018). "In SAG-stimulated human medulloblastoma cells, stable, lentiviral shRNA inhibition of DYRK1A moderately reduced GLI1 and PTCH mRNA expression by 55 and 40 percent, respectively." (PMID 26784250, 2016). "As assay system we employed HH-responsive, SMO-inhibitor sensitive human medulloblastoma cells (DAOY) and measured changes in the expression of the known HH target genes GLI1 and PTCH as quantitative read-out for pathway activity." (PMID 26784250, 2016). "BRD4 inhibitor JQ1 or I-BET151 treatment inhibits GLI1 and GLI2 expression and growth of hedgehog-driven tumors in vitro and in vivo, such as basal cell carcinoma, medulloblastoma and atypical teratoid rhabdoid tumor." (PMID 26343727, 2015). "Compound screens have successfully identified compounds that activate Gs-associated GPCRs, resulting in inhibition of Shh signaling downstream of Gli1 and antagonists of the Gi-coupled receptor CXCR4 have demonstrated efficacy in medulloblastoma models." (PMID 26258793, 2015). "Thus, disrupting the Gli1–Hck feedback loop may inhibit progression of Shh-type medulloblastoma." (PMID 26619401, 2015). "Statistical analysis by the Fisher's test revealed significant correlations of GLI1 expression with PAX6 (p = 0.015) and NKX2.2 (p = 0.015) expression in medulloblastoma cell lines." (PMID 21059263, 2010).
medulloblastoma (continued). "In this study, we sought to understand the regulatory roles of GLI1, the immediate downstream activator of the Shh signaling pathway on its downstream target genes PTCH1, Cyclin D2, Plakoglobin, NKX2.2 and PAX6 in medulloblastoma and astrocytic tumors." (PMID 21059263, 2010). "The promoted Gli1 expression by YAP enhances its transcriptional activity, thus establishing an Hh-YAP-Gli signaling loop that significantly increases the migration and proliferation of cancer cells in osteosarcoma and medulloblastoma." (PMID 40673277, 2025). "In medulloblastoma (MB), BCL6 could lead to epigenetic inhibition of the GLI family zinc finger 1/2 (GLI1 and GLI2), which are the critical effectors of the sonic hedgehog (Shh) pathway." (PMID 37060074, 2023). "Unlike a previous study implying that elevated BRD4 expression mediates SMOi resistance by activating Gli1 transcription, we report that JQ1 inhibition suppresses SMOi-resistant SHH medulloblastoma in the absence of significant Gli1 expression." (PMID 36688010, 2022). "To explore whether the Shh pathway mediates the antitumor effect of metformin on medulloblastoma, after the treatment of Daoy cells with SAG (100 nm) and metformin (3 mm), we found that the SAG can attenuate the inhibitory effect of metformin on Gli-1." (PMID 36278239, 2022). "Upon long-term treatment with LDE225, the RNA levels of the known SHH pathway genes Ptch1, Smo, Gli1, and Gli2 were equivalent to those in control-treated tumors in SD-CSC medulloblastomas, indicating continued activation of the SHH pathway consistent with acquired mutations in this pathway." (PMID 36688010, 2022). "Similarly, in mouse models of SHH medulloblastoma, it was recently shown that phenformin elicited a potent antitumor effect independently of AMPK and of phosphorylation of the AMPK substrate GLI1." (PMID 35804992, 2022). "Additionally, GLI1 serves as an excellent biomarker for tumor response in BCC and Hh-active medulloblastoma." (PMID 34572373, 2021). "However, Hh pathway components, particularly GLI1, are ideal predictive biomarkers for SMO inhibitor therapy in several cancers, including BCC and Shh-medulloblastomas." (PMID 34572373, 2021). "In addition, treatment of a medulloblastoma mouse model with I-BET151, a Brd4 inhibitor, reduced Gli1 expression, cell proliferation and tumor growth, indicating epigenetics drives Hh activation in cancer." (PMID 29563577, 2018). "Together, these findings reveal a novel noncanonical GLI1 regulation and provide a potential therapeutic target for the treatment of cancers with aberrant Hh pathway activation, such as medulloblastoma." (PMID 29662197, 2018). "In turn, this possibility suggests that mechanisms involving interaction between GLI1 and PIN1 may represent potential therapeutic targets in SHH-driven medulloblastoma tumorigenesis." (PMID 30314361, 2018). "Similarly, in medulloblastoma, the role of AMPK as both an inhibitor of GLI1 and SHH signaling (tumor-suppressive effect) as well as a promoter of CNBP and polyamine metabolism (pro-tumorigenic effect) supposes a dual role for AMPK in this disease context." (PMID 30360486, 2018). "To functionally validate the activation of the SHH pathway, we confirmed the upregulation of the transcription factor GLI1, a main target gene of the pathway, in ITD-positive samples compared to the normal brain and a medulloblastoma of the WNT subtype by qRT-PCR." (PMID 27825128, 2016). "Although Sufu has a pivotal role in Hh signaling and mutations in Sufu are present in SHH medulloblastoma, the mRNA of Sufu was found to be not reduced in the SHH subtype, whereas Gli1 was found to be drastically increased." (PMID 27234298, 2016).
medulloblastoma (continued). "In addition, we found that GLI1 up-regulated CXCR4 expression in MCF-7 cells, as previously reported in medulloblastoma cells and pancreatic cancer cells." (PMID 26413813, 2015). "GLI1 mRNA expression varied in 3 orders of magnitude among the GBM patients of the same cohort showing a single continuous distribution—unlike the discrete high/low-GLI1 mRNA expressing clusters of medulloblastoma (MB)." (PMID 25775002, 2015). "Our data confirm the tumor-suppressive role of Gli1 in neuroblastoma as opposed to its oncogenic potential in basal cell carcinoma and medulloblastoma." (PMID 23900341, 2013). "Similarly, in medulloblastoma primary tumor samples, only expression of NKX2.2 showed significant correlation with GLI1 expression (p = 0.004)." (PMID 21059263, 2010). "However, high levels of GLI1 correlated with high levels of Cyclin D2 and PTCH1 in medulloblastoma cell lines and tumor samples." (PMID 21059263, 2010). "Several studies showed that GLI1 amplification is absent in pediatric medulloblastoma, a common childhood brain cancer." (PMID 21119888, 2010). "GLI1 appears to up-regulate PTCH1 expression in both medulloblastomas and astrocytomas, and remaining genes tested, namely, Cyclin D2, Plakoglobin, PAX6, and NKX2.2, only in medulloblastomas." (PMID 21059263, 2010). "The drugs GANT61 and HPI-1 target Gli1 and Gli2 but have not been tested in medulloblastoma." (PMID 40094009, 2025). "Gli1 expression was significantly inhibited as shown by RT-qPCR and the tumor cell growth was completely blocked by GSK-J4 as measured by ATP assay, suggesting that GSK-J4 is more effective in inhibiting the growth of medulloblastoma cells compared to CGNP cells." (PMID 36531063, 2022). "Similarly, over-expression of associated network clusters enriched for SHH pathway members, GLI1, PTCH1 and PTCH2, was exclusive to human SHH medulloblastoma, and expression levels were significantly higher than in CD133+ NSCs, NPCs and all other controls used in this study." (PMID 25412507, 2014). "However, direct regulation of these genes by GLI1 has not been studied in major brain tumors such as medulloblastomas and astrocytomas." (PMID 21059263, 2010). "In our study, we have silenced expression of GLI1 using a small interfering RNA (siRNA), followed by the determination of gene expression patterns of PTCH1, Cyclin D2, Plakoglobin, NKX2.2 and PAX6 in 14 cell lines and 41 primary medulloblastoma and astrocytoma tumor samples." (PMID 21059263, 2010). "However, several studies report that GLIs (especially GLI1 and GLI2) can be regulated by the cross talk with other signaling pathways in various types of cancers including melanoma, gastric cancer, colon cancer, multiple myeloma, medulloblastoma, pancreatic cancer, glioblastoma, and osteosarcoma." (PMID 32245491, 2020). "Furthermore, mutation of the putative miR-324-5p complementary seed sites within both the GLI1 and SMO 3′UTRs prevented miR-324-5p from exerting its repressive effects on the constructs, confirming miR-324-5p acts directly on the human SMO and GLI1 3′UTR, as proposed in medulloblastoma." (PMID 30193893, 2019). "Furthermore, one of the top targets, FOXS1, a gene encoding a transcription factor previously implicated in nervous system development, was shown to act in a negative feedback loop limiting the cellular effects of GLI1 in medulloblastoma and rhabdomyosarcoma cells." (PMID 30098229, 2018). "Additionally, GLI1 induces the expression of SNAIL1 transcription factor in GNP which in turn directly regulates the transcription of the oncogene N-MYC, which is hypothesized to mediate the oncogenic transformation of GNP into medulloblastoma." (PMID 26633513, 2015). "Interestingly, both mRNA and protein levels of Hck were significantly higher in medulloblastoma compared with normal cerebellum and NIH3T3 cells, which may contribute to the abnormally high Shh/Gli1 activities in Shh-type medulloblastoma and the uncontrolled proliferation of these cells." (PMID 26619401, 2015).
medulloblastoma (continued). "After siRNA-mediated GLI1 silencing in Daoy and U87MG cell lines, expression of PTCH1 decreased, compared with scrambled siRNA-transfected and untransfected cell lines, which may suggest positive regulation of PTCH1 by GLI1 in medulloblastomas and astrocytomas." (PMID 21059263, 2010). "Part 1 included participants with advanced solid tumors including BCC and medulloblastoma, regardless of SMO or GLI1 expression levels." (PMID 35954384, 2022). "In the SHH-induced mouse model of medulloblastoma, highly expressed nonreceptor tyrosine kinase HCK phosphorylates GLI1, resulting in enhancement of GLI1-mediated target gene activation." (PMID 30675521, 2019). "EGFR is not as well studied in medulloblastoma though there is data to support a synergism between EGFR and Hedgehog signaling in SHH tumors resulting in stabilization of the Gli1 protein." (PMID 29880060, 2018). "Clinical trials based on the administration of SMO antagonists have demonstrated effectiveness in HH-driven tumors, such as BCC and medulloblastoma; however, the therapeutic efficacy of SMO inhibitors may not be effective in tumors having non-canonical activation of GLI1." (PMID 33958721, 2021).
pancreatic cancer (122 papers, 2009 to 2025). "In human pancreatic cancer cells, the RNA interference of Gli1 and Gli2 causes β-catenin mis-localization." (PMID 40508185, 2025). "They found that it reduced GLI1 stability and dampened GLI1-mediated transcriptional activity in a pancreatic cancer cell line harbouring KRAS mutations." (PMID 38920995, 2024). "In this study, we seek to explore the role of Gli1-derived exosomal circ-0011536 in the development of neurological changes in pancreatic cancer and investigate the underlying molecular mechanism by regulation of the Hh signaling pathway." (PMID 38041128, 2023). "Mutated KRAS is observed in >90% of pancreatic cancer cases and its downstream mediator, GLI1, is responsible for KRAS–induced pancreatic development/transformation." (PMID 26988754, 2017). "Whereas inhibition of the MAPK pathway by the MEK1/2 inhibitor U0126 decreases Gli1 stability and suppresses the Gli1-mediated transcriptional activity in a KRAS-mutated pancreatic cancer cell line." (PMID 29163356, 2017). "Genetic analysis of pancreatic cancers showed mutations in GLI1 with clear functional relevance to neoplasia." (PMID 26633513, 2015). "Recently, nuclear GLI1 expression was shown to be closely correlated with nuclear expression of NFκB in pancreatic cancer, and both were associated with shorter overall survival and worse outcome." (PMID 25252859, 2014). "Hh pathway components may exhibit mutations in GLI1 and GLI3, as seen in pancreatic cancer, or in the GLI1 amplification gene, as seen in glioblastoma." (PMID 39547513, 2024). "In human cancer, GREM1 expression has been demonstrated in pancreatic stellate cells (PSCs), and is driven by Shh → Gli1 signaling, enabling pancreatic cancer progression." (PMID 40277903, 2025). "In pancreatic cancer, GLI1 regulates EMT through specific target genes such as TGF-β, Ras, Wnt, P13K/AKT, and S100A4." (PMID 37139482, 2023). "The effects of Gli1 in promoting pancreatic cancer proliferation and invasion were verified in this study, and our results were consistent with those reported in the literature." (PMID 38041128, 2023). "In gastrointestinal cancers and pancreatic cancers driven by KRAS/BRAF mutation, GLI-1 is over-activated." (PMID 37304485, 2023). "HH signaling pathway influences multiple tumor cell behavior in pancreatic cancer through regulating Gli1 expression." (PMID 37596267, 2023). "In a murine model of pancreatic cancer, GLI-1 binds to the IL-6 promoter and increase its expression, leading to a more aggressive phenotype." (PMID 38188300, 2023). "We therefore investigated the individual and combined contributions of GLI1-3 to pancreatic cancer progression." (PMID 35867772, 2022). "Specifically, SMAD2 and 4 were shown to physically interact with GLI1 along with PCAF in pancreatic cancer cells, and enhance GLI1-dependent BCL2 transcription through PCAF-mediated epigenetic activation." (PMID 36556332, 2022). "These antiproliferative effects, together with the induction of apoptosis, were mediated by the inhibition of the Akt/Gli1 signaling cascade, a well recognized oncogenic axis in pancreatic cancer." (PMID 34439102, 2021). "This is similar to a report showing that the MEK-ERK arm is required for an oncKRAS-mediated block of GLI1 expression in fibroblasts and pancreatic carcinoma cell lines." (PMID 34172934, 2021). "Our data revealed that CM from Cav-1-knockdown PSCs increased DNA synthesis and upregulated Gli-1 expression in pancreatic cancer cells." (PMID 32377291, 2020). "IHC studies conducted on clinical pancreatic tumor specimens confirmed the correlated expression of GLI1 and MUC5AC." (PMID 33266161, 2020). "Hypoxia has been shown to increase HH pathway activation through the upregulation of SHH, Smoothened (SMO), and GLI1 transcription in a ligand-independent manner, leading to enhanced invasiveness of pancreatic cancer." (PMID 32707920, 2020).